OTUB1 (OTU deubiquitinase, ubiquitin aldehyde binding 1)
Diseases named in the same sentence as OTUB1 in open-access papers (continued):
Sharing a sentence is not in itself a finding about the gene and the disease.
cystic fibrosis (2 papers, 2022 to 2025). Autosomal recessive disorder caused by pathogenic variants in the CFTR gene (cystic fibrosis transmembrane conductance regulator), which encodes a chloride and bicarbonate channel expressed in epithelial cells, and follow the diagnosis criteria. "As a proof-of-concept, a bifunctional molecule linking a ligand that covalently engages the DUB OTUB1 to a chemical moiety that binds ΔF508-CFTR in cystic fibrosis could stabilize ΔF508-CFTR in an OTUB1-dependent manner." (PMID 36420167, 2022).
glioblastoma (2 papers, 2024 to 2025). The most malignant astrocytic tumor (WHO grade IV). "Previous studies have shown that OTUB1 may be an oncogene in glioblastoma multiforme (GBM), but its specific regulatory mechanism remains unclear." (PMID 39006090, 2024).
lung fibrosis (2 papers, 2020 to 2023). "Therefore, the restoration of SERCA2a may also inhibit inflammatory responses during the earlier phase of lung fibrosis by blocking the OTUB1 and NF-κB-dependent immune signaling." (PMID 32587955, 2020).
lupus nephritis (2 papers, 2012 to 2024). Glomerulonephritis in the context of systemic lupus erythematosus. "Utilizing Ferrostatin-1, a ferroptosis inhibitor, we have shown that it mitigates podocyte injury induced by OTUB1 deficiency, thereby suggesting a promising therapeutic strategy for lupus nephritis." (PMID 39500879, 2024). "In our study, we demonstrated that OTUB1 exerts a significant protective effect against lupus nephritis through the targeted regulation of the ferroptosis pathway." (PMID 39500879, 2024). "In this study, we investigated the potential molecular mechanisms of OTUB1 in podocyte injury in lupus nephritis." (PMID 39500879, 2024). "OTUB1 overexpression was detected in the mesangial area of glomeruli in some immunocomplex mediated nephritides such as IgA nephropathy, acute diffuse proliferative glomerulonephritis and lupus nephritis by immunohistochemistry." (PMID 22279542, 2012).
lymph node metastasis (2 papers, 2016 to 2018). "A univariate Cox analysis implied that FIGO staging, lymph node metastasis, FOXM1, and OTUB1 correlated with survival." (PMID 27167337, 2016). "OTUB1 expression gradually increased with the advance of stage, tightly correlated with FIGO staging, lymph node metastasis, tumor size, and recurrence (p<0.05)." (PMID 27167337, 2016).
Parkinson disease (2 papers, 2016 to 2023). A progressive degenerative disorder of the central nervous system characterized by loss of dopamine producing neurons in the substantia nigra and the presence of Lewy bodies in the substantia nigra and locus coeruleus. "In fact, Uchl1, Otub1 and Atxn3 are involved in neurodegenerative diseases in human, namely Parkinson's disease and cerebellar ataxia, thus indicating a relevant role in neurodegeneration." (PMID 26934049, 2016).
renal carcinoma (2 papers, 2022 to 2023). A carcinoma arising from the epithelium of the renal parenchyma or the renal pelvis. "OTUB1 mediates the deubiquitination of FOXM1 to promote renal cancer tumor progression." (PMID 36339263, 2022).
renal cell carcinoma (2 papers, 2020). "We aim to investigate the effect and mechanism of OTUB1/FOXM1 on RCC (renal cell carcinoma) progression." (PMID 32257108, 2020).
Sepsis (2 papers, 2021 to 2023). Sepsis is defined as life-threatening organ dysfunction caused by a dysregulated host response to infection. "Since DCs also play an important role in sepsis and contribute to LPS-induced immunopathology, mice with DCs with intact OTUB1 function produced significantly more proinflammatory disease-promoting cytokines and succumbed significantly earlier to LPS challenge." (PMID 32024978, 2021).
Tauopathies (2 papers, 2017). "We next analyzed the modulatory effect of Otub1 on Tau in primary neurons, as relevant cell type for the study of Tauopathies and AD." (PMID 28083634, 2017). "Otub1 and particularly Otub1 inhibitors, currently under development for cancer therapies, may therefore yield interesting novel therapeutic avenues for Tauopathies and AD." (PMID 28083634, 2017). "Furthermore, Otub1 was shown to contribute directly to tau pathology, since Otub1 expression in primary neurons leads to enhanced tau aggregation and increased levels of oligomeric tau forms, which might be important given that tau oligomers have emerged as the pathogenic species in tauopathies." (PMID 28848737, 2017). "This highlighted Otub1 as a potential entry point to better understand the link between the UPS and Tauopathies." (PMID 28083634, 2017).
acute liver failure (1 paper, 2021). Rapid deterioration of liver function causing encephalopathy and coagulopathy. "To further study the role of OTUB1 in TNF responses of hepatocytes, we employed the DGal/LPS model, which induces TNF-dependent hepatocyte death and acute liver failure." (PMID 33712742, 2021).
atherosclerosis (1 paper, 2025). A disease characterized by the build-up of fatty material and calcium deposition in the arterial wall resulting in partial or complete occlusion of the arterial lumen. "Additionally, Otubain-1 (OTUB1) and OTUB2 belong to the same subfamily, which was previously reported to play important roles in the regulation of bone homeostasis and atherosclerosis 30-31." (PMID 39776804, 2025).
autoimmune disease (1 paper, 2022). A disorder resulting from loss of function or tissue destruction of an organ or multiple organs, arising from humoral or cellular immune responses of the individual to their own tissue constituents. "OTUB1 has been identified to regulate NK/CD8+ T cell activation, autoimmune diseases, PD-L1-mediated immune evasion, and viral or bacterial infection-related immune responses." (PMID 35864871, 2022).
benign breast tumours (1 paper, 2023). "By contrast, benign breast tumours and adjacent breast tissues showed comparable protein expression of OTUB1 and CCN6." (PMID 37608493, 2023).
bladder tumors (1 paper, 2024). "OTUB1 significantly promotes the growth of bladder tumors in vivo, while XAV-939 restrains the increasing tendency; overexpressed β-catenin also achieves the same promoting effects on bladder tumor growth." (PMID 39113709, 2024).
breast tumour (1 paper, 2023). "Malignant tumours had lower levels of OTUB1 and CCN6 than did benign tumours and normal breast tissues, and the levels of OTUB1 were positively correlated with CCN6 levels in breast tumours." (PMID 37608493, 2023). "Deletion of OTUB1, accompanied by reduced CCN6 protein abundance, enhanced the growth of 4T1 cells in vitro and in vivo, and the effect of OTUB1 deletion was abolished by CCN6 overexpression, unambiguously showing that OTUB1 inhibits breast tumour via stabilizing CCN6." (PMID 37608493, 2023).
colitis (1 paper, 2025). Inflammation of the colon. "By examining intestinal tissues from DSS-induced colitis mice, we found a significant increase in OTUB1 protein levels in the Fex treatment group relative to those in the DSS model group." (PMID 40681992, 2025).
endometrial cancer (1 paper, 2023). Primary or metastatic malignant neoplasm involving the endometrium (mucous membrane that lines the endometrial cavity). "Further study showed OTUB1 directly deubiquitinates ERα and decreases its catalytic activity in Ishikawa endometrial cancer cells." (PMID 38264570, 2023). "This work hints at a tumor-inhibiting role of OTUB1 in ER-positive breast cancer and endometrial cancer." (PMID 38264570, 2023).
endometriosis (1 paper, 2022). The growth of functional endometrial tissue in anatomic sites outside the uterine body. "We, therefore, established an endometriosis model using OTUB1-knockout mice to investigate the effect of OTUB1 on the development of endometriosis in vivo." (PMID 36339263, 2022). "To determine the role of OTUB1 in the growth of endometriosis tissue, we examined the effect on endometriosis cell growth when OTUB1 expression was altered." (PMID 36339263, 2022). "Taken together, our study reveals the theoretical basis for the OTUB1/HSF1 axis as a potential target for the treatment of endometriosis." (PMID 36339263, 2022). "The results confirmed that OTUB1 promoted EMT in endometriosis, which is consistent with our previous findings." (PMID 36339263, 2022). "In this study, we demonstrate that OTUB1 promotes the development of endometriosis via deubiquitination of HSF1." (PMID 36339263, 2022). "In addition, OTUB1 enhances glycolysis and epithelial-mesenchymal transition of endometriosis cells, leading to promote proliferation, migration, and invasion of endometriosis cells." (PMID 36339263, 2022). "In addition, more work is needed to explore other roles of OTUB1 in the mechanism of endometriosis development." (PMID 36339263, 2022). "In this study, OTUB1 enhanced the proliferation, migration, and invasion of endometriosis cells." (PMID 36339263, 2022). "Together, OTUB1 promotes epithelial-mesenchymal transition in endometriosis cells." (PMID 36339263, 2022). "In conclusion, OTUB1 promotes glycolysis in endometriosis cells." (PMID 36339263, 2022). "In summary, OTUB1 promotes the development of endometriosis by up-regulating HSF1." (PMID 36339263, 2022). "We also find that OTUB1 promotes the growth and invasion of endometriosis cells." (PMID 36339263, 2022). "The progression of endometriosis is inhibited in an OTUB1-knockout mouse model." (PMID 36339263, 2022). "Taken together, OTUB1 promotes the proliferation and migration of endometriosis cells." (PMID 36339263, 2022). "The results further show that OTUB1 promotes the development of endometriosis in vivo and in vitro." (PMID 36339263, 2022). "The function of OTUB1 as a deubiquitinating enzyme acting on other substrates in endometriosis is still unknown." (PMID 36339263, 2022). "We established an endometriosis model using OTUB1-knockout mice." (PMID 36339263, 2022). "The results showed that OTUB1 deletion inhibited the growth of endometriosis lesions." (PMID 36339263, 2022). "Thus, the knockdown of OTUB1 inhibits the development of endometriosis in vivo." (PMID 36339263, 2022). "Therefore, OTUB1 may serve as a novel biomarker and provide new ideas and approaches for the treatment of endometriosis." (PMID 36339263, 2022). "OTUB1/HSF1 axis may become a new therapeutic target for endometriosis." (PMID 36339263, 2022). "Moreover, the development of endometriosis is inhibited in an OTUB1-knockout mouse model." (PMID 36339263, 2022). "Our data showed that overexpression of OTUB1 altered the expression levels of EMT-related factors and promotes EMT in endometriosis cells." (PMID 36339263, 2022). "However, the role of OTUB1 in endometriosis remains unclear." (PMID 36339263, 2022).
Fanconi anemia (1 paper, 2023). Fanconi anemia (FA) is a hereditary DNA repair disorder characterized by progressive pancytopenia with bone marrow failure, variable congenital malformations and predisposition to develop hematological or solid tumors. "The DUB proteins USP1, OTUB1, UCHL5, USP7, and PSMD14 were reported to contribute to double-strand break repair, USP1 to Fanconi anemia pathway, USP1 and USP7 to translesion repair, USP7 and USP47 to base excision repair, and USP7 and USP45 to nucleotide excision repair." (PMID 37892185, 2023).
glomerulonephritis (1 paper, 2012). A renal disorder characterized by damage in the glomeruli. "Since DCN is an important antagonizing factor for glomeruli inflammation, it is suggestion that OTUB1 may be another novel regulator involved in the pathogenesis of glomerulonephritis." (PMID 22279542, 2012). "The aim of this study is to investigate the role of OTUB1 expression in MC and its relationship with DCN during glomerulonephritis." (PMID 22279542, 2012).
glomerulosclerosis (1 paper, 2012). A hardening of the kidney glomerulus caused by scarring of the blood vessels. "Thus, OTUB1 revealed to be a possible novel regulator during glomerulonephritides, which would facilitate degradation of DCN and enhance the vicious circle characterized by increased TGF-β1 production and matrix deposition in developing glomerulosclerosis." (PMID 22279542, 2012).
hepatitis B virus infection (1 paper, 2020). A viral infection caused by the hepatitis B virus. "Recently, some researchers have proved that OTUB1 could attenuate interferon response to hepatitis B virus infection." (PMID 33537306, 2020).
Hyperglycemia (1 paper, 2021). An increased concentration of glucose in the blood. "Consistent with hyperglycemia-induced reduced expression of YB-1 in H9c2 cells and in diabetic mice, Co-IP studies showed an impaired interaction between YB-1 and OTUB1 in H9c2 cells incubated with HG, whereas aPC treatment significantly preserved YB-1/OTUB1 interaction." (PMID 34778410, 2021).
intracerebral hemorrhage (1 paper, 2022). A cerebrovascular disorder characterized by bleeding into one or both cerebral hemispheres including the basal ganglia and the cerebral cortex. "Ubiquitin thioesterase OTUB1 is expressed mainly in the Lewy bodies of brain and exerts an anti-apoptotic effect against intracerebral hemorrhage." (PMID 35562751, 2022).
kidney cancer (1 paper, 2023). Primary or metastatic malignant neoplasm involving the kidney. "In addition, OTUB1 also increases the kidney cancer cell tolerance of chemotherapeutic drugs oxaliplatin and doxorubicin through RAPTOR." (PMID 38264570, 2023). "This study collectively delineated a Src-OTUB1–mTORC1 axis in kidney cancer." (PMID 38264570, 2023).
lentivirus infection (1 paper, 2021). Virus diseases caused by the Lentivirus genus. "The Annexin V/PI staining and flow cytometric analysis revealed that AVT-induced MM cell apoptosis was partly ablated by overexpression of Otub1 via lentivirus infection." (PMID 33627137, 2021).
listeriosis (1 paper, 2021). A bacterial infection caused by Listeria monocytogenes. "RIPK1 immunoprecipitates from livers of both mouse strains contained RIPK3 with an increased amount in OTUB1LPC-KO mice indicating that OTUB1-deficiency increases necroptosis during listeriosis." (PMID 33712742, 2021). "Here, we identify OTUB1 as an inhibitor of hepatocyte necroptosis in listeriosis and upon TNF stimulation." (PMID 33712742, 2021). "Thus, OTUB1 prevented lethal listeriosis, liver necrosis, and production of TNF." (PMID 33712742, 2021). "Next, we identified the cell population producing increased amounts of TNF in the absence of OTUB1 during listeriosis." (PMID 33712742, 2021). "In accordance to the deubiquitinase activity of OTUB1 on K48-linked polyubiquitin chains of c-IAP1, we detected enhanced K48-linked polyubiquitination of c-IAP1 in the livers of OTUB1LPC-KO mice upon Listeria infection, which was independent of MLKL." (PMID 33712742, 2021). "Considering the increased in vivo degradation of c-IAP1 in the absence of OTUB1, we studied whether OTUB1 protects hepatic c-IAP1 against proteasomal degradation in listeriosis and upon D-Gal/TNF treatment." (PMID 33712742, 2021).
liver inflammation (1 paper, 2021). "The critical in vivo importance of OTUB1 as a hepatocyte-intrinsic inhibitor of necroptosis is illustrated by the lethal exacerbation of bacterial hepatitis and DGal/LPS-induced liver inflammation." (PMID 33712742, 2021).
lupus (1 paper, 2024). "Decreased OTUB1 expression is consistently observed in the glomeruli of LN patients and lupus-prone mice." (PMID 39500879, 2024). "Specifically, we examined OTUB1 expression in the renal tissues of MRL/lpr mice, a well-established murine model of lupus." (PMID 39500879, 2024).
metastatic prostate carcinoma (1 paper, 2015). A carcinoma that arises from the prostate gland and has spread to other anatomic sites. "Our results suggest that drugs targeting the catalytic activity of OTUB1 could potentially be used as therapeutics for metastatic prostate cancer." (PMID 25623341, 2015).
metastatic tumor (1 paper, 2014). "Because high OTUB1 expression in primary CRC tissues is associated with lymph node status and distant metastasis, we analyzed whether OTUB1 was highly expressed in lymph node or metastatic tumor tissues." (PMID 25431208, 2014).
Nephropathy (1 paper, 2012). A nonspecific term referring to disease or damage of the kidneys. "Immune-reaction staining demonstrated that OTUB1 expression was diversely present in nephropathy samples, but with few positive cells in the normal glomeruli." (PMID 22279542, 2012).
non-alcoholic fatty liver disease (1 paper, 2024). "OTUB1 also inhibits the polyubiquitination of TRAF6 and the subsequent activation of the ASK1 signaling pathway, playing a critical protective role in non-alcoholic fatty liver disease." (PMID 39500879, 2024).
Osteopenia (1 paper, 2023). Osteopenia is a term to define bone density that is not normal but also not as low as osteoporosis. "Moreover, Otub1 mRNA level was significantly downregulated in bones from osteoporotic mice, and restoring OTUB1 levels through an AAV9-delivered system in ovariectomy-induced osteoporotic mice attenuated osteopenia." (PMID 37024477, 2023).
osteoporosis (1 paper, 2023). A condition of reduced bone mass, with decreased cortical thickness and a decrease in the number and size of the trabeculae of cancellous bone (but normal chemical composition), resulting in increased fracture incidence. "Furthermore, OTUB1 expression is downregulated during osteoporosis, and restoring OTUB1 levels attenuates bone loss in an osteoporotic mouse model established by ovariectomy (OVX)." (PMID 37024477, 2023). "Our study provides new insights into the physiological function of OTUB1 in osteogenesis and indicates that targeting osteoblast-specific OTUB1 is a potential therapeutic strategy in osteoporosis." (PMID 37024477, 2023). "The positive role of OTUB1 in osteogenesis suggests its potential application in osteoporosis via upregulation of osteogenesis." (PMID 37024477, 2023). "The positive role of OTUB1 in osteogenesis prompted us to examine its potential application in osteoporosis using local AAV9-delivered systems." (PMID 37024477, 2023). "Recently, a more efficient integrating tetrahedral DNA nanostructure drug delivery system was established, which could be a better carrier to test the effects of osteoblast-specific OTUB1 in the treatment of osteoporosis." (PMID 37024477, 2023). "Furthermore, OTUB1 is downregulated during osteoporosis and its overexpression in knee joints alleviates osteoporosis in ovariectomized mice." (PMID 37024477, 2023). "This decreased OTUB1 expression in postmenopausal osteoporosis and age-related osteoporosis prompted us to explore whether the exogenous expression of Otub1 could alleviate osteoporosis in OVX mice in vivo." (PMID 37024477, 2023). "Based on this, we established an osteoporosis mouse model by ovariectomy (OVX) and found that the mRNA level of Otub1 in BMSCs derived from OVX mice was markedly decreased compared with the sham-operated (Sham) control." (PMID 37024477, 2023). "Taken together, our results suggest that OTUB1 positively regulates osteogenic differentiation and mineralization in bone homeostasis by controlling FGFR2 stability, which provides an optical therapeutic strategy to alleviate osteoporosis." (PMID 37024477, 2023). "In this study, we unveil the positive role of OTUB1 in osteoblast-mediated bone formation by maintaining FGFR2 stability and the osteogenesis effects of OTUB1 provide an optical therapeutic strategy to alleviate osteoporosis." (PMID 37024477, 2023).